UBE2C (ubiquitin conjugating enzyme E2 C)
Diseases named in the same sentence as UBE2C in open-access papers (continued):
Sharing a sentence is not in itself a finding about the gene and the disease.
breast carcinoma (continued). "Taken together, these results revealed an overexpression of both UBE2S and UBE2C and a downregulation of Numb in breast cancer, indicating the oncogenic effects of UBE2S and UBE2C and the tumor suppressive role of Numb in breast cancer." (PMID 36860312, 2023). "For example, there has been an increase in UBE2C levels in various types of cancer (e.g. breast cancer, esophageal squamous cell carcinoma, and lung cancer), and its overexpression correlates with poor prognosis in patients." (PMID 36964266, 2023). "More recently, it has been reported that the circular RNA circ_0059457 is responsible for UBE2C-driven breast cancer cell migration, invasion, and metastasis through an miR-140-3p-dependent mechanism." (PMID 37958776, 2023). "UBE2S and UBE2C also demonstrated increased expression in breast cancer with a more advanced grade and stage, while Numb showed the opposite trend." (PMID 36860312, 2023). "In this study, we identified 8 cDEGs (COL11A1, COL10A1, CD36, ACACB, CD24, PLK1, UBE2C, and PDK4) as breast cancer (BC)-causing HubGs from 3 microarrays and one scRNA-seq dataset by the protein-protein interaction (PPI) network analysis of 46 cDEGs." (PMID 37893423, 2023). "In particular, high expression of UBE2C correlated with an unfavorable prognosis for different cancer types such as breast cancer, thyroid carcinoma, cervical cancer, and gastric cancer." (PMID 38102624, 2023). "Previous research manifested that UBE2C is highly expressed in pancreatic cancer, breast cancer, and esophageal squamous cell carcinoma." (PMID 37840753, 2023). "By using Oncomine data analysis and Kaplan–Meier plotter survival analysis, we further analyzed the prognostic effects of UBE2S, UBE2C, and Numb in breast cancer patients." (PMID 36860312, 2023). "Accumulating evidence also suggested that the high expression of UBE2C is strongly related to poor prognosis in patients with breast cancer, lung adenocarcinoma or gastric cancer." (PMID 37535572, 2023). "Both qRT-PCR and western blot confirmed increased UBE2S and UBE2C, as well as decreased Numb expression, in breast cancer cell lines compared to MCF10A." (PMID 36860312, 2023). "To explore the functional role of UBE2S, UBE2C, and Numb in ER+ breast cancer, we compared the mRNA levels of the three genes in ER+ and ER− breast cancer through Oncomine dataset analysis." (PMID 36860312, 2023). "Upregulation of UBE2C in breast cancer, non-small-cell lung cancer, and glioma is discovered to promote the malignant progression of tumor cells." (PMID 37840753, 2023). "The expression of UBE2S and UBE2C was decreased and Numb was increased in ER+ breast cancer; we thus explored the prognostic values of UBE2S, UBE2C, and Numb in ER+ breast cancer patients." (PMID 36860312, 2023). "In the field of breast cancer, some research found that UBE2C was regulated by estrogen-independent growth, which has been proved to be a tumorigenic factor for ER-positive HER2 negative BC cells." (PMID 36069832, 2022). "Cross-species genome comparison suggested that the genomic changes of UBE2T and UBE2C are related to the occurrence, development, and invasion of breast cancer." (PMID 35578283, 2022). "UBE2C is overexpressed in breast cancer tissues and functions as a cellular proto-oncogene to promote the proliferation of breast cancer cells." (PMID 36551544, 2022). "Existing evidence has shown that the overexpression of UBE2C aggravates patient prognosis by promoting breast cancer cell proliferation." (PMID 36551544, 2022). "Accumulating evidence has shown that UBE2C is highly expressed and acts as a proto-oncogene in various types of human cancers, such as breast cancer, lung cancer, esophageal cancer, colon cancer, and thyroid cancer." (PMID 35804892, 2022). "Meantime, overexpression of UBE2C has been demonstrated in various human malignancies, such as breast carcinoma, lung cancer, gastric cancer, etc." (PMID 35804892, 2022).
breast carcinoma (continued). "The relationship between DNA hypomethylation and the mRNA overexpression of UBE2C, as well as the prognostic value of UBE2C hypomethylation, have previously been reported in a genome-wide study of CpG methylation in breast cancer samples." (PMID 35804892, 2022). "Of note, UBE2C, an E2 ubiquitin-conjugating enzyme, has been reported to promote the progression of various cancers, including breast cancer." (PMID 36551544, 2022). "UBE2C is overexpressed in various types of cancer including cervical cancer, breast cancer and non-small cell lung cancer (NSCLC) participates in the progression of these tumors." (PMID 36385010, 2022). "In breast cancer, while upregulation of UBE2C promotes drug resistance, knockdown of UBE2C sensitizes the cells to radiation and chemotherapeutic drugs, such as tamoxifen, doxorubicin, epirubicin, and docetaxel." (PMID 34199813, 2021). "UBE2C promotes drug resistance in breast cancer, as the UBE2C blockade enhances tumor cell sensitivity to doxorubicin." (PMID 33805973, 2021). "UBE2C was highly expressed in diverse tumors when compared with respective normal tissue, such as breast cancer, lung cancer, colon cancer, liver cancer, thyroid cancer, prostate cancer." (PMID 33630978, 2021). "UBE2C is generally considered as an important tumor biomarker, as it is overexpressed in breast cancer, thyroid cancer, lung cancer, gastric cancer, and other tumor tissues, but shows low expression in normal tissues." (PMID 34488675, 2021). "UBE2C overexpressed in various human cancers, including breast cancer and is correlated with tumor malignancy." (PMID 33313822, 2021). "The high expression of UBE2C in breast cancer was reported to be an independent prognostic factor associated with increased risk of disease recurrence and death." (PMID 34675265, 2021). "Knockdown of UBE2C sensitizes epirubicin- and docetaxel-resistant breast cancer cells to chemotherapeutic agents." (PMID 32899896, 2020). "Upregulation of UBE2C is considered to be a potential molecular marker for the prognosis of breast cancer and advanced colon cancer with liver metastases." (PMID 32963620, 2020). "UBE2C exerts oncogenic effects on various human solid cancers including breast cancer, HCC, colon cancer, nasopharyngeal carcinoma (NPC) and, among others." (PMID 32397206, 2020). "The expression level of UBE2C is very high in various human cancers, such as breast cancer, ovarian cancer, head and neck squamous cell carcinoma (HNSCC) and melanoma, suggesting that UBE2C is associated with tumorigenesis." (PMID 32899896, 2020). "The results of these studies were also supported by decreased cell proliferation in UBE2C knockdown cells in cases of nasopharyngeal carcinoma and breast cancer." (PMID 33396624, 2020). "UBE2C depletion markedly increased the cytotoxicity of tamoxifen by inducing apoptosis in HR+/HER2– breast cancer cells." (PMID 32039034, 2019). "In this study, we showed that UBE2C is involved in cell cycle regulation, and that UBE2C overexpression contributes to estrogen-independent growth in HR+/HER2– breast cancer cells." (PMID 32039034, 2019). "In breast cancer, UBE2C knockdown increased the sensitivity of cancer cells to epirubicin and docetaxel and promoted the apoptosis induced by these two drugs through impaired the increased BCL-2 and MDR-1 expression levels." (PMID 30914455, 2019). "UBE2C is considered to be a crucial factor upregulated in various malignancies, including breast cancer, melanoma, esophageal squamous cell carcinoma, colorectal cancer and gastric cancer." (PMID 31788359, 2019). "The mRNA expression levels of UBE2C in four breast cancer subtypes were compared using 819 FFPE tissues from patients with different LN status." (PMID 32039034, 2019). "The median UBE2C mRNA expression was lower in HR+/HER2– breast cancers with pN0 and pN1 tumors than in other subtypes." (PMID 32039034, 2019).
breast carcinoma (continued). "In vitro functional experiments in HR+/HER2– breast cancer cells showed that UBE2C expression is a tumorigenic factor, and that estrogen upregulated UBE2C mRNA and protein by directly binding to the UBE2C promoter region." (PMID 32039034, 2019). "We also evaluated the expression status of UBE2C and investigated the molecular mechanism underlying the role of UBE2C regulation in HR+/HER2– breast cancer progression." (PMID 32039034, 2019). "The clinical significance of UBE2C in breast cancer was investigated by analyzing UBE2C mRNA expression in invasive breast cancer tissues." (PMID 32039034, 2019). "On the basis of the association between UBE2C expression and clinical outcomes in HR+/HER2– breast cancer, we examined the expression status of UBE2C in different breast cancer subtypes." (PMID 32039034, 2019). "It has been reported that the expression level of UBE2C is positively correlated with tumor grade and poor prognosis in the adrenal cancer, breast cancer, colon cancer, lung cancer and ovarian cancer." (PMID 31422942, 2019). "The role of estrogen receptor α (ERα) in the regulation of UBE2C mRNA expression in HR+/HER2– breast cancer was evaluated by analyzing the recruitment of ERα to the promoter region of UBE2C in MCF-7 cells by ChIP-PCR." (PMID 32039034, 2019). "Another study in breast cancer indicated that UBE2C down-regulation promoted the chemosensitivity of epirubicin and docetaxel resistant breast cancer cells." (PMID 29137415, 2017). "With regard to DFS, the expression of MMP11 and UBE2C were independent prognostic factors in HR−/HER2+ breast cancer." (PMID 28409241, 2017). "UBE2C expression in ductal carcinoma was higher than most other types of breast cancer (all P < 0.05) except breast adenocarcinoma with squamous metoplasla and medullary breast carcinoma." (PMID 29021715, 2017). "The elevated expression of IBSP, COL11A1, MYBL2 and UBE2C in breast cancer has previously been reported to directly correlate with tumor progression." (PMID 27359054, 2016). "We investigated the carcinogenic role of UBE2C in MCF-7 breast cancer cells with UBE2C knockdown; UBE2C knockdown downregulated cell proliferation and activated the cellular apoptosis pathway to inhibit cell colony formation." (PMID 24699941, 2014). "Development of a UBE2C detection tool and targeting drug therapy would be of benefit to clinical practice in breast cancer diagnosis and treatment." (PMID 24699941, 2014). "To understand the effect of UBE2C in breast cancer cell growth and migration, we overexpressed or knocked down UBE2C in MCF-7 cells." (PMID 24699941, 2014). "UBE2C as a suggested malignant breast-cancer biomarker was evaluated in paraffin-embedded surgical specimens in previous studies." (PMID 24699941, 2014). "In conclusion, we demonstrated that UBE2C biomarker expression in core biopsy specimens from mammography provides information to evaluate breast lesions or early breast carcinoma." (PMID 24699941, 2014). "To evaluate the practical application of UBE2C in early breast cancer diagnosis, we measured UBE2C mRNA and protein expression in vacuum-assisted breast core biopsies and analyzed the relation between UBE2C expression and clinical features." (PMID 24699941, 2014). "We provide a theoretical basis for UBE2C as a potential biomarker candidate or theraputic target for early breast cancer." (PMID 24699941, 2014). "Pathology diagnosis showed similar results, with lower UBE2C expression with benign fibrocystic disease than DCIS/lobular carcinoma in situ and IDC malignant lesions." (PMID 24699941, 2014). "Ubiquitin-conjugating enzyme 2C (UBE2C) contributes to ubiquitin-mediated proteasome degradation of cell cycle progression in breast cancer." (PMID 24699941, 2014). "We also investigated the carcinogenic role of UBE2C in the breast cancer cell cycle by its overexpression or knockdown ectopic expression." (PMID 24699941, 2014).
breast carcinoma (continued). "Knockdown of UBE2C expression by shRNA interference demonstrated the carcinogenesis role of UBE2C in proliferation, migration, and survival in breast cancer cell activities." (PMID 24699941, 2014). "We recently identified and validated UBE2C RNA as a prognostic marker in 252 node-positive (N+) breast cancers by means of a microarray study." (PMID 19513072, 2009). "According to the following points, we strongly believe that UBE2C is a prognostic marker of breast cancer." (PMID 19513072, 2009). "The aim of this study was to validate UBE2C protein as a prognostic marker in N+ breast cancer by immunohistochemistry (IHC)." (PMID 19513072, 2009). "Of these candidate oncogenes, several, notably TOP2A, PNMT and UBE2C, have appeared in prognostic gene expression signatures, thus re-emphasizing their important role in breast cancer." (PMID 17925008, 2007). "Considering that cell cycle arrest is a typical characteristic of cellular senescence, we further validated whether the inhibition of UBE2C could induce senescence in breast cancer." (PMID 40729680, 2025). "FOXM1 was identified as the most likely transcriptional factor of UBE2C in breast cancer cells." (PMID 40729680, 2025). "Moreover, the expression of UBE2C was upregulated at higher pathological stages and histological grades of breast cancer." (PMID 40729680, 2025). "Given that UBE2C plays an important role in regulating the cell cycle and senescence in breast cancer cells, we examined whether UBE2C could affect the sensitivity of breast cancer cells to doxorubicin." (PMID 40729680, 2025). "UBE2C was significantly upregulated in almost all cancers types including breast cancer." (PMID 40729680, 2025). "Based on the results of GSEA enrichment, we speculated whether the knockdown of UBE2C could affect the cell cycle of breast cancer cells, and flow cytometry was conducted to analyze the cell cycle distribution." (PMID 40729680, 2025). "Moreover, the inhibition of UBE2C downregulated the expression of TOP2A to sensitize breast cancer cells to doxorubicin and aggravate doxorubicin‐induced senescence." (PMID 40729680, 2025). "Conversely, knockdown of FOXM1 downregulated the expression of UBE2C in breast cancer cells." (PMID 40729680, 2025). "Moreover, aberrant UBE2C expression was found to be transcriptionally regulated by forkhead box protein M1 (FOXM1) in breast cancer." (PMID 40729680, 2025). "Although the oncogenic role of UBE2C in breast cancer has been partially elucidated, the exact mechanisms and downstream signaling of UBE2C remain unclear." (PMID 40729680, 2025). "Similarly, the protein expression of UBE2C was also positively correlated with that of TOP2A in breast cancer." (PMID 40729680, 2025). "In vivo, UBE2C inhibition also sensitized breast cancer cells to doxorubicin." (PMID 40729680, 2025). "Moreover, UBE2C inhibition sensitized breast cancer cells to doxorubicin by downregulating the expression of TOP2A." (PMID 40729680, 2025). "The prognosis significance of UBE2C in breast cancer based on multiple GEO datasets." (PMID 40729680, 2025). "UBE2C inhibition suppressed breast cancer cell proliferation." (PMID 40729680, 2025). "Overexpression of FOXM1 could upregulate UBE2C expression at the mRNA level and protein levels in breast cancer cells." (PMID 40729680, 2025). "Furthermore, GESA was conducted to analyze the functional enrichment of UBE2C‐correlated genes in breast cancer against Gene Ontology (GO) categories and pathways from the Kyoto Encyclopedia of Genes and Genomes (KEGG)." (PMID 40729680, 2025). "Moreover, the inhibition of UBE2C promoted Parkin‐mediated K63‐linked ubiquitination of TOP2A, leading to its proteasomal degradation and thus sensitizing breast cancer cells to doxorubicin." (PMID 40729680, 2025). "UBE2C confers resistance to chemotherapy and targeted therapy in breast cancer cells." (PMID 41009526, 2025).
breast carcinoma (continued). "All in all, UBE2C inhibition could promote Parkin‐mediated K63‐linked ubiquitination of TOP2A to induce senescence and increase doxorubicin sensitivity in breast cancer." (PMID 40729680, 2025). "In vivo, inhibition of UBE2C sensitized breast cancer cells to doxorubicin." (PMID 40729680, 2025). "Inhibition of UBE2C suppressed proliferation and induced senescence in breast cancer cells." (PMID 40729680, 2025). "The mRNA expression of UBE2C positively correlated with that of TOP2A in breast cancer." (PMID 40729680, 2025). "UBE2C inhibition suppressed the proliferation and induced senescence in breast cancer cells." (PMID 40729680, 2025). "Taken together, these results showed that inhibition of UBE2C could promote Parkin‐mediated K63‐linked ubiquitination of TOP2A to induce senescence and sensitize breast cancer cells to doxorubicin." (PMID 40729680, 2025). "Moreover, UBE2C inhibition also sensitized breast cancer cells to doxorubicin by downregulating TOP2A and aggravating doxorubicin‐induced cellular senescence." (PMID 40729680, 2025). "The expression of UBE2C was transcriptionally regulated by FOXM1 in breast cancer cells." (PMID 40729680, 2025). "However, the prognostic effects as well as the collective regulatory mechanisms of both UBE2S and UBE2C in breast cancer remain to be elucidated." (PMID 36860312, 2023). "Moreover, there have been multiple reports that UBE2C is an oncogene and correlates with poor survival outcomes in lung cancer, gastric cancer, hepatocellular carcinoma, and breast cancer." (PMID 38102624, 2023). "UBE2C: Ubiquitin-binding enzyme E2C (UBE2C) may be oncogenic for the progression of breast cancer genes." (PMID 37468832, 2023). "However, a significant increase in Numb expression was observed by silencing UBE2S or UBE2C expression in breast cancer cells at both protein and mRNA levels." (PMID 36860312, 2023). "Similarly, ubiquitin-conjugating enzyme E2 C (UBE2C) also plays a role in regulating the radiosensitivity of breast cancer cells, though the exact mechanism requires further exploration." (PMID 38137461, 2023). "UBE2C overexpression has been shown to have a prognostic value in breast cancer." (PMID 37958776, 2023). "Oncomine, Cancer Cell Line Encyclopedia (CCLE), the Human Protein Atlas (HPA) database, qRT-PCR, and Western blot analyses were utilized to analyze UBE2S/UBE2C and Numb expression in various cancer types and their respective normal controls, breast cancer tissues, and breast cancer cell lines." (PMID 36860312, 2023). "Knockdown of UBE2C sensitized the cells to pharmacological treatments with irinotecan in colorectal cancer and increased the sensitivity of cancer cells to epirubicin and docetaxel in breast cancer." (PMID 35332135, 2022). "Moreover, UBE2C was reported high in breast cancer, indicated to be an independent prognostic factor connected with the recurrence and death, and associated with a shorter survival period of breast cancer patients." (PMID 35409038, 2022). "In addition, a previous study has highlighted the prognostic significance of UBE2C mRNA expression in the breast cancer patients since high UBE2C mRNA expression functions as an independent adverse prognostic factor for relapse and death." (PMID 36551544, 2022). "Interestingly, expressions of CHEK1 and UBE2C were positively correlated with each other in luminal A breast cancer subtype, suggesting the existence of a potential co-regulatory network for both genes." (PMID 35903365, 2022). "In addition, growing researches suggested that UBE2C was dysregulated in prostate cancer, cervical cancer, breast cancer, and so on." (PMID 34950739, 2021). "As it has been shown by recent, encouraging data from a study carried out on the urine of subjects with breast cancer, the analysis of UBE2C transcript levels could become a sensitive marker that can be exploited in diagnostics." (PMID 32192022, 2020).